REST (RE1 silencing transcription factor)
Diseases named in the same sentence as REST in open-access papers (continued):
Sharing a sentence is not in itself a finding about the gene and the disease.
Lyme disease (1 paper, 2015). Lyme disease (named after the towns in the USA where the disease was first identified) is a bacterial infection caused by Borrelia burgdorferi. "We performed a mutagenic survey of all the histidine and glutamine residues in ResT that are conserved across both relapsing fever and Lyme disease causing Borrelia species." (PMID 26007659, 2015).
lymph node metastasis (1 paper, 2010). "We find that the REST–less gene signature is closely associated with the presence of the truncated REST4 splice variant and that REST status is an important predictor of poor prognosis that correlates with increased lymph node metastasis and early disease recurrence." (PMID 20548947, 2010).
manganism (1 paper, 2024). "These novel findings suggest that dopaminergic REST in the nigrostriatal pathway is critical in protecting against Mn toxicity, underscoring REST as a potential therapeutic target for treating manganism." (PMID 39178947, 2024).
meningioma (1 paper, 2025). A generally slow growing tumor attached to the dura mater. "However, further validation is required to determine whether REST functions as a tumor suppressor gene in meningioma." (PMID 41184266, 2025).
metastatic cancers (1 paper, 2022). A carcinoma which has spread from the original site of growth to another anatomic site. "Additionally, REST’s role in other metastatic cancers has yet to be explored." (PMID 35177031, 2022).
microcephaly (1 paper, 2016). A congenital or acquired developmental disorder in which the circumference of the head is smaller than normal for the person's age and sex. "Despite these results, a recent study points to a role for REST in human neurogenesis and microcephaly through regulation of REST by a factor, ZNF335, mutated in patients with a severe form of microcephaly." (PMID 26745185, 2016). "Because a previous study indicated that loss of REST was associated with microcephaly, we asked whether this was also true for our RestGT mice." (PMID 26745185, 2016). "Additionally, microcephaly results from dysregulation of a REST/BAF170/Pax6 repressor complex during neurogenesis." (PMID 26745185, 2016).
multiple sclerosis (1 paper, 2021). A progressive autoimmune disorder affecting the central nervous system resulting in demyelination. "Our results demonstrate that REST upregulation represents a new pathogenic mechanism for the synaptic dysfunctions observed under neuroinflammatory conditions and identify the REST pathway as therapeutic target for EAE and, potentially, for multiple sclerosis." (PMID 33589593, 2021).
nasopharyngeal carcinoma (1 paper, 2013). A carcinoma arising from the nasopharyngeal epithelium. "A recent study revealed that HAUSP counterbalances REST (also known as neuron restrictive silencer factor, NRSF) ubiquitination and prevents nasopharyngeal carcinoma (NPC) differentiation." (PMID 23483195, 2013).
Neurofibrillary tangles (1 paper, 2023). Pathological protein aggregates formed by hyperphosphorylation of a microtubule-associated protein known as tau, causing it to aggregate in an insoluble form. "REST directly targets and represses genes that mediate phospho-tau accumulation in 3xTg mice, including the tau kinases GSK3β and CDK5 which have been implicated in neurofibrillary tangle formation." (PMID 37919281, 2023).
nicotine addiction (1 paper, 2021). "KEGG pathway analysis revealed that the REST-associated DEGs were mainly enriched in neuroactive ligand-receptor interaction, ECM-receptor interaction, and nicotine addiction." (PMID 34859007, 2021).
Niemann-Pick Type C disease (1 paper, 2013). "In non-HD models, lithium downregulated REST binding and protein levels in a rat fetal alcohol syndrome model whereas valproate upregulated REST transcription in medulloblastoma cells, but neuroprotectively repressed REST in the Niemann-Pick Type C disease NPC1 knockout mouse." (PMID 24248060, 2013).
Obesity (1 paper, 2018). Accumulation of substantial excess body fat. "HMG20A regulates metabolism-secretion coupling genes in beta cells and could be also involved in beta cell plasticity through PAX4 and REST, regulating phenotypic changes needed for beta cells in order to respond to different physiological situations as pregnancy and obesity." (PMID 29449530, 2018).
oral cancer (1 paper, 2023). "However, when APP/PS1 combination was compared with APP/PS1 + PE, we identified 772 DEGs, which were found to be enriched in EIF3K and REST transcription factors, both shown to regulate the mTOR signaling pathway in adipocyte yeast and oral cancer cells, respectively." (PMID 39081972, 2023).
pancreatitis (1 paper, 2020). Inflammation of the pancreas. "Importantly, pancreatitis-damaged tissue from both REST KO and Cre control mice demonstrated a loss of acinar cells and a gain of ductal cells." (PMID 32080178, 2020). "The severe degree of injury in REST KO mice during pancreatitis could overpower the dependence on REST during induced ADM through an alternative mechanism." (PMID 32080178, 2020).
renal cell carcinoma (1 paper, 2021). "In this study, we evaluated the expression patterns of REST in renal cell carcinoma and found that its expression is lower in tumor tissues compared to normal tissues." (PMID 33834072, 2021).
rotator cuff tears (1 paper, 2022). "This study showed an association between the occurrence of rotator cuff tears and several genes, including LAIR2, REST, and CRIPAK." (PMID 36292186, 2022). "Through this study, we newly identified SNPs of genes LAIR2, CRIPAK, and REST that were significantly altered in patients with rotator cuff tears." (PMID 36292186, 2022).
scrapie (1 paper, 2017). A fatal disease of the nervous system in sheep and goats, characterized by pruritus, debility, and locomotor incoordination. "Herein, we studied the expression and distribution of REST in scrapie-infected hamsters, and REST expression and associated changes of the Akt-mTOR Wnt-β-catenin signaling pathways." (PMID 28515679, 2017). "To investigate the expression of REST protein in scrapie-infected hamsters, we infected hamsters by intraperitoneal inoculation of 263 K prions and examined the amount of PK-resistant PrP in the brains of terminally sick hamsters firstly." (PMID 28515679, 2017). "Here we further demonstrated that REST is lost from the nucleus in the brains of scrapie-infected hamsters and taken up in autophagosomes." (PMID 28515679, 2017).
skin cancer (1 paper, 2023). "Some examples of cancers with reduced expression levels of REST include lung, breast, prostate, and skin cancers." (PMID 36984538, 2023).
teratocarcinoma (1 paper, 2012). A germ cell tumor characterized by the presence of an embryonal carcinoma component and a teratoma component. "By shRNA mediated knockdown, DNA microarray expression analysis and ChIP analysis, we show that a number of genes are co-regulated by REST and RNF2 in human teratocarcinoma NT2-D1 cells." (PMID 22396653, 2012). "We performed size-exclusion chromatography of nuclear extracts from the human teratocarcinoma cells, NT2-D1 (left part) and HEK 293 cells and performed immunoprecipitation of REST from pools of different fractions as indicated (right part)." (PMID 22396653, 2012). "Here we present evidence for an interaction between the transcription factor REST, PRC1, and PRC2 and show that RNF2 and REST co-regulate a number of neuronal genes in human teratocarcinoma cells (NT2-D1)." (PMID 22396653, 2012).
type 2 diabetic (1 paper, 2018). "Systems biology approaches identified HNF1A, PDX1 and REST as drivers of gene co-expression modules correlated with impaired insulin secretion or glucose tolerance, and 14 out of 19 differentially expressed type 2 diabetic islet signature genes were enriched in these modules." (PMID 29185012, 2018).
tumor (110 papers, 2005 to 2026). "REST expression undoubtedly plays a crucial role in cancer, and is associated with tumor progression-related processes, including cell migration, invasion, and metastasis." (PMID 40006989, 2025). "REST expression was associated with high tumor aggressiveness and invasiveness, as well as chemotherapy resistance." (PMID 38711090, 2024). "We previously showed that the loss of REST (RE-1 Silencing Transcription factor), a tumor suppressor, in fibroids leads to activation of PI3K/AKT-mTOR pathway." (PMID 39314474, 2024). "In the past few years, the association between REST and tumor also has aroused increasing attention." (PMID 36810892, 2023). "Here, we report that the administration of SRRM4 ASO causes anti-tumor effects through the modification of alternative splicing from sREST to REST." (PMID 36650528, 2023). "A better understating of how loss of REST leads to increased tumor progression or aggressive clinical behavior requires an extensive look into REST target genes." (PMID 35177031, 2022). "Orthotopic implantation of v-MYC immortalized murine cerebellar progenitor cells that constitutively express human REST causes tumor formation in the mouse cerebellum." (PMID 34758854, 2021). "Inhibition of REST in DIPG caused a substantial decline in tumor vasculature, as measured by decreased CD31 and VEGFR2 staining, and reduced tube formation." (PMID 32486064, 2020). "DIPGs are vascularized tumors and interestingly, REST loss in DIPG cells also caused a substantial decline in tumor vasculature as measured by a decrease in CD31 and VEGFR2 staining." (PMID 29435175, 2018). "Intriguingly, we have traced the loss of the tumor suppressor to the presence of a variant of the REST protein normally found in the brain following seizures, which represents a unique and attractive therapeutic target." (PMID 20548947, 2010). "To accomplish this, we developed a gene signature comprised of direct targets of REST repression with which to interrogate tumor microarray datasets to search for a loss of REST function." (PMID 20548947, 2010). "In an unbiased tumor suppressor screen, REST loss conferred anchorage-independent growth upon immortalized human mammary epithelial cells." (PMID 20548947, 2010). "In light of the connection we have established between REST and Wnt, it is possible that REST plays an important role in regulating Wnt signaling and that loss of REST function leads to tumor initiation." (PMID 18959480, 2008). "For instance, disruption of the Rb tumor suppressor pathway causes CIN by upregulating Mad2 whereas inactivation of the REST tumor suppressor causes CIN by decreasing expression of Mad2." (PMID 18545697, 2008). "In addition to the deregulated REST function in tumor cells, REST is one of the many host factors implicated in the life cycle of HIV, HSV-1, and KSHV." (PMID 40006989, 2025). "The oldest of these (PD37585) bore an embryonic mosaic mutation in one copy of the REST tumour suppressor gene, which could be detected at a low allele fraction in other normal tissues." (PMID 40442086, 2025). "Expanding on the difference in REST expression between EC and control samples, and the aggressive nature that the loss of REST manifests, may help determine the role of REST as a potential prognostic marker and putative tumor suppressor." (PMID 39273639, 2024). "We hypothesized that REST expression would be decreased in EC tissue and cell lines and that REST deficiency would contribute to the hallmarks of tumor progression and spread." (PMID 39273639, 2024). "We hypothesized that the loss of PRICKLE1 expression in LSMCs is mechanistically linked to the loss of REST and smooth muscle tumor development in the uterus." (PMID 39314474, 2024). "These investigations suggest that REST may be a hub that extensively regulates tumor occurrence and development and can serve as a diagnostic and therapeutic target." (PMID 37892159, 2023).
tumor (continued). "Indeed, the decrease in tumor vascular pericyte coverage in the REST-KO tumors was associated with increased tumor hypoxia and apoptosis." (PMID 32486064, 2020). "KIT and REST have been implicated as tumor and metastasis suppressors in colorectal cancer." (PMID 30429477, 2018). "Previous studies support the idea that REST is a tumor suppressor outside of the nervous system, but tumors generally reflect the loss of more than one tumor suppressor." (PMID 26745185, 2016). "We tested the possibility that the abrogation of REST function may be due to a loss of REST mRNA by comparing transcript levels in REST–less and RESTfl tumor samples." (PMID 20548947, 2010). "Surprisingly, a REST‐dependent increase in the expression of the proangiogenic transcription factor E26 oncogene homolog 1, and its target gene encoding the vascular endothelial growth factor receptor‐1, was observed in MB cells, which coincided with their localization at the tumor vasculature." (PMID 33469989, 2021). "Since LSD1 and REST elevation was associated with a higher incidence of metastasis in patients, we carried out a more detailed examination of the “cellular adhesion and movement” category, which identified a number of significantly altered genes related to tumor cell migration." (PMID 30227871, 2018). "REST function is regulated at multiple post-transcriptional levels during differentiation and disease and so we needed a method of detecting a loss of REST function in a tumor, regardless of the underlying mechanism responsible for the loss of the tumor suppressor." (PMID 20548947, 2010). "All these studies clearly indicate the role of REST in tumor suppression and growth inhibition in cancer." (PMID 40006989, 2025). "Binding site accessibility of REST, a transcriptional repressor of neuroendocrine differentiation was higher in cfDNA corresponding to tumor samples with increased REST expression (Spearman’s r = − 0.33, P = 0.061)." (PMID 40001151, 2025). "Apart from these tissues, the role of REST is extensively studied in various cancers where it exhibits a dual function, both as a tumor suppressor and tumor promoter." (PMID 40006989, 2025). "Increased PI3K signaling was also observed in cells which lack REST expression and was attributed to their transformed phenotype which clearly depicted the tumor-suppressive role of REST in CRC." (PMID 40006989, 2025). "In vivo, combined JTC-801 and CQ treatment significantly reduced tumor growth and restored REST expression in PCa xenografts, validating the therapeutic potential of this combinatorial strategy." (PMID 41353213, 2025). "Except for one tumor with copy-neutral LOH 4q including the mutant REST locus, all other tumors had independent second somatic REST mutations." (PMID 40340749, 2025). "REST, a transcriptional repressor of neuronal genes, has been described as a tumor suppressor in several malignancies." (PMID 40410286, 2025). "REST, an inhibitory transcription factor, has been reported with both tumor promotor and tumor suppressor effects." (PMID 39039049, 2024). "We then explored the relationship between REST and MMP24 in addition to the association of REST expression with patient and tumor characteristics." (PMID 39273639, 2024). "In cervical cancer, REST expression was significantly lower in cancer samples compared to benign samples, suggesting a possible function as a tumor suppressor." (PMID 39273639, 2024). "The loss of REST by β–TrCP mediated ubiquitination and proteasomal degradation is suggested to result in PI3K/AKT dependent tumor cell proliferation and cell survival." (PMID 39314474, 2024). "Increased REST expression decreased apoptosis and increased invasive properties of GBM cells, while knockdown of REST in GBM xenografts led to either cell differentiation or cell death significantly impairing tumor growth." (PMID 38711090, 2024).
tumor (continued). "Recently, we showed that conditional deletion of Rest in mouse uterus leads to UL phenotype, including tumor development, gene expression analogous to human UL, and revealed a direct role for REST in aberrant estrogen and progesterone signaling." (PMID 39314474, 2024). "We also evaluated three different functions of tumor spread and metastasis, including proliferation, migration, and invasion to help characterize the role of REST in EC function." (PMID 39273639, 2024). "REST behaves like a tumor suppressor, decreasing the aggressiveness of 22rv1 cells, probably through the repression of EMT and the neuroendocrine phenotype." (PMID 38542313, 2024). "REST is a major tumor suppressor that functions by epigenetic regulation of a multitude of its target genes through the recruitment of chromatin modifying enzymes to gene promoters." (PMID 39314474, 2024). "Our results support the fact that, in our model, REST behaves like a tumor suppressor, decreasing the aggressive behavior of 22rv1 cells, probably through the repression of the EMT process and the neuroendocrine phenotype." (PMID 38542313, 2024). "We identified RE1 silencing factor (REST) as a potential biomarker for SCLC associated with low neuroendocrine features, more active anti-tumor immunity, and prolonged survival." (PMID 39231924, 2024). "Acting as a molecular scaffold, HOTAIR bridges PRC2 and LSD1/CoREST/REST complexes and recruits them to the promoter regions of distant tumor suppressor and metastasis suppressor genes." (PMID 38339237, 2024). "CDX13, the only non-NE POU2F3 subtype CDX8 was the only model with REST expressed throughout the tumor, in which VM vessels were abundant (VM vessel score 38%) and co-localized with REST." (PMID 37455012, 2023). "Repression of SRRM4 mRNA induced modified alternative splicing producing REST, followed by anti-tumor effects." (PMID 36650528, 2023). "RE1-silencing transcription factor (REST) is a tumor suppressor, and its splicing isoform (sREST) is abnormally expressed by SRRM4 and causes carcinogenesis with neuroendocrine phenotype in SCLC." (PMID 36650528, 2023). "Taken together, SRRM4 ASO exhibited anti-tumor effects by suppressing SRRM4 mRNA expression through the modification of alternative splicing from sREST to REST." (PMID 36650528, 2023). "We show for the first time REST directly regulates CEMIP and loss of REST contributes to HA depolymerization and tumor progression by upregulating CEMIP." (PMID 35177031, 2022). "In an effort to understand the mediators of aggressive tumor growth, invasion and metastasis in RESTless cancers, we analyzed available gene expression datasets for REST target gene signatures." (PMID 35177031, 2022). "REST elevation increased secretion of proangiogenic factors and upregulated genes with potential to drive an endothelial cell‐like phenotype in tumor cells." (PMID 33469989, 2021). "A DyLight 594–labeled lectin perfusion assay was used to evaluate the effect of REST down-regulation on tumor vascular perfusion." (PMID 32486064, 2020). "HIF-1α expression was significantly increased in both R1106 and R1606 REST-KO tumor tissues compared with RC-control tumors." (PMID 32486064, 2020). "In conclusion, the inhibition of REST reduced tumor vessel pericytes and altered vasculature morphology and functionality." (PMID 32486064, 2020). "In this study, we show that down-regulating REST using CRISPR/Cas9 impacts tumor growth and metastasis by targeting tumor blood vessel structure and function." (PMID 32486064, 2020). "Our results are in line with these findings but also show that the down-regulation of REST reduced both endothelial cells and the tumor vascular pericytes." (PMID 32486064, 2020). "Tumor vessels in the REST-knockout tumors had a punctate appearance with significantly decreased tumor vascular pericytes, decreased perfusion, and increased permeability." (PMID 32486064, 2020).